TNF (tumor necrosis factor)
Diseases named in the same sentence as TNF in open-access papers (continued):
Sharing a sentence is not in itself a finding about the gene and the disease.
enteritis (70 papers, 2010 to 2026). Inflammation of the small intestine. "During enteritis, significant infiltration of inflammation‐associated factors such as TNF‐α, IL‐1β, and IL‐6 causes damage to intestinal epithelial cells, triggering an increase in intestinal permeability." (PMID 40661137, 2025). "These cause activation of lymphocytes to secrete pro-inflammatory cytokines such as interferon-γ, interleukin-4, and tumor necrosis factor-α, causing damage to the villi and resulting in enteritis." (PMID 32617423, 2020). "TNF-α is a pro-inflammatory cytokine produced mainly by macrophages and monocytes, which is involved in the inflammatory response, and when its level is too high, it increases intestinal permeability and causes an enteritis response." (PMID 38496307, 2024). "Tumor Necrosis Factor-alpha (TNF-α) represents a central mediator in the inflammatory cascade of enteritis, playing a crucial role in disease pathogenesis through its pro-inflammatory actions." (PMID 40284867, 2025). "Our findings demonstrate that D-CONGA-Q7 significantly reduces the levels of pro-inflammatory cytokines TNF-α, IL-6, and IL-18, effectively alleviating small intestinal inflammation in a mouse model of enteritis induced by K88 (ETEC) exposure." (PMID 40136483, 2025). "The levels of IL-1β (p < 0.0001), IL-6 (p < 0.01), and TNF-α (p < 0.0001) in the serum of mice in the enteritis model group were significantly elevated compared with the CON group, indicating that DSS can trigger systemic inflammatory responses in mice." (PMID 40238292, 2025). "The results indicated that the inhibitory effect of Homo on enteritis was closely associated with RLN, MAPK, TNF, AKT1, and CASP3 signaling pathways." (PMID 40529132, 2025). "IL-6, IL-1β, and TNF-α are considered biomarkers of inflammation and are positively correlated with the severity of enteritis." (PMID 41007944, 2025). "Because of their pro-inflammatory and immunomodulatory functions, TNF-α and IL-8 play a key role in the pathogenesis of C. perfringens-induced enteritis." (PMID 40869997, 2025). "This experiment used ELISA, PCR, and WB to detect the expressions of PUN and the core targets of bacterial enteritis, i.e., TNF and IL-6, through network pharmacology." (PMID 37246319, 2024). "The results showed that PUN and CEF significantly down-regulated the expressions of TNF-α and IL-6 proteins in the serum and intestinal wall of mice with enteritis, alleviating the destruction of intestinal wall barrier proteins by inflammatory factors." (PMID 37246319, 2024). "In the enteritis patient, TNF-α not only increase the infiltration of neutrophils, but also cause damage to the intestinal barrier." (PMID 36778862, 2023). "Tumor necrosis factor α (TNF-α) and interleukin 1β (IL1β) are typically pro-inflammatory cytokines, and up-regulation of their gene expression is closely associated with enteritis." (PMID 37520524, 2023). "In the enteritis patient, TNF-α and IL-1β not only increase the infiltration of neutrophils, but also cause damage to the intestinal barrier." (PMID 35401451, 2022). "Baicalin can protect the small intestinal epithelial cells of rats against TNF-α-induced injury and alleviate enteritis-related diarrhea." (PMID 35449393, 2022). "At present, it is known that TNF-α, IL-1β, and IL-6 are known to be closely related to the progression of enteritis." (PMID 36076306, 2022). "In a mouse model of Salmonella enteritis induced joint inflammation, increased levels of inflammatory cytokines IL-17 and TNF-α were observed in the mesenteric lymph node and synovium respectively." (PMID 33537028, 2020).
enteritis (continued). "Neutralizing IL-17 in mice infected with S. enteritis, prevented synovitis and curbed the increase in TNF-α, suggesting the role of IL-17 in gut and joint inflammation." (PMID 33537028, 2020). "The remaining patient who presented with fever, recurrent oral ulcers, and severe enteritis, experienced persistent symptoms while receiving conventional treatment, and she was eventually administered anti-TNF-alpha therapy." (PMID 31296171, 2019). "Quantitative PCR analysis showed that CGA suppressed the expression of pro-inflammatory factors including interferon-γ (Ifn-γ), interleukin-7 (Il-7), tumor necrosis factor-α (Tnf-α), and upregulated the anti-inflammatory cytokines interleukin-10 (Il-10) in LPS-induced enteritis mice." (PMID 41788896, 2026). "During the occurrence of enteritis, the up-regulation of pro-inflammatory cytokines (including IL-6 and TNF-α) acts as a protective inflammatory response and leads to inflammation response through the down-regulation of anti-inflammatory cytokines (including IL-10)." (PMID 40564253, 2025). "After 24 hours of induction of LPS, enteritis cells could secrete higher inflammatory factors TNF-α, IL-6 and IL-1β." (PMID 40948782, 2025). "High percentage of dietary SBM could induce enteritis in L. crocea, showing increased proinflammatory cytokine production (IL-1β, IL-6, and TNF-α) and decreased anti-inflammatory cytokine expression (IL-4/13a, IL-4/13b, and TGF-β)." (PMID 40688731, 2025). "Table highlighted the diagnostic importance of estimated pro-inflammatory cytokines and APPs, indicating their sensitivities as biomarkers for sheep enteritis, particularly emphasizing IL-1α, IL-6, TNF-α, and Hp due to their highest specificities, LRs, PPVs, and accuracy rates." (PMID 39394128, 2024). "In this experiment, the levels of TNF-α, IL-1β, IL-6, and IL-10 in the mouse colon were measured using ELISA kits to assess the impact of different treatments on inflammatory factors in murine enteritis." (PMID 39697653, 2024). "The cytokines TNF-α, IL-1β, and IL-6 represent critical pro-inflammatory substances of enteritis." (PMID 38998101, 2024). "Studies in aquatic animals have shown that similarly to butyric acid, glutamine and its dipeptide can downregulate the mRNA expression of TNF-α and IL-1β in the intestine of hybrid grouper and turbot, and effectively inhibit the fish enteritis induced by soybean meal." (PMID 37266423, 2023). "Furthermore, IL-10 levels were much lower in enteritis mice than in the normal group, while TNF-α, IL-1β, and IL-6 levels were dramatically enhanced after DSS administration." (PMID 37375702, 2023). "Likewise, negative health-related impacts in the gut of turbot were reported after feeding high levels of corn gluten meal, inducing enteritis, and decreasing intestinal immunity, by increasing the inflammatory cytokine transcripts IL-1β, IL-8, and TNF-α." (PMID 35565636, 2022). "Colonic inflammation is dependent on TNFα signaling, whereas TNFα deficiency is able to ameliorate colonic inflammation, but is not sufficient to prevent Paneth cell loss or enteritis in the small intestine." (PMID 34141714, 2021). "Co‐culture with intraperitoneal macrophages from mice with DSS‐induced enteritis significantly increased the levels of inflammatory factors (IL‐6, IL‐11, IL‐22, TNF‐α) in colonic epithelial cells compared to macrophages from healthy mice, whereas GW4868 eliminated this difference." (PMID 33569850, 2021). "In addition, we observed a distinct pattern of gut dysbiosis, increased bacterial translocation, minimal enteritis, and elevated systemic levels of the pro-inflammatory cytokine TNF-α." (PMID 31822775, 2019). "However, oral inoculation of those pigs with F4+ ETEC/VTEC/EPEC resulted in enteritis in the small intestine and excessive systemic inflammatory responses including increased production of the proinflammatory cytokine TNF-α." (PMID 26384321, 2015).
enteritis (continued). "Following DSS-induced enteritis, there was a significant increase in the protein levels of CXCL10 and TNF-α, coupled with a notable decrease in IL10 and CCL17." (PMID 38774206, 2024). "Pun primarily uses the PI3K-Akt and TNF signaling pathways, as well as other cancer and inflammation-related pathways identified through KEGG pathway analysis, to treat bacterial enteritis." (PMID 37246319, 2024). "The present study found that treatment of SCP-Se NPs more effectively reduced LPS-induced elevation of IL-1β, IL-6, and TNF-α relative to SCP, closely correlated with its anti-enteritis effects." (PMID 36899787, 2023). "Fraxetin was reported to mitigate the levels of IL-1β, IL-6, TNF-α and prostaglandin E2, improve the content of superoxide dismutase (SOD) and IL-10 in rats with enteritis." (PMID 37161415, 2023). "In the present study, the expression of pro-inflammatory factor (TNF-α) was upregulated by dietary FMG group, which revealed the occurrence of glycinin-induced enteritis." (PMID 37187750, 2023). "The number of goblet cells and inflammatory cells was reduced, and the levels of IL-1β, TNF-α, NO, and PGE2 were significantly decreased in the Tregs-infusion group compared to those in the enteritis group (p<0.05)." (PMID 30364052, 2018). "The levels of IL-1β, TNF-α, NO and PGE2 were decreased compared to those in the Treg-transferred mice and were significantly different compared to the levels in the enteritis group (P<0.05)." (PMID 30364052, 2018). "We demonstrated that expression of TNF-α and IL-1β mRNAs were alldecreased by treating with curcumin or NAC in rat enteritis model." (PMID 20885979, 2010). "Despite the absence of enteritis signs, an increase in macrophages/like TNF-α+ cells in the intestine mucosa indicated immune stimulation in the BSF10 group." (PMID 41975991, 2026). "Both Que and RU.521 could significantly reduce the protein levels of CXCL10 and TNF-α while increasing the protein levels of IL10 and CCL17 following the induction of enteritis." (PMID 38774206, 2024). "In the present study, TS1 also reduced the SE-induced increase in the expression of pro-inflammatory cytokines (IL-1β, IL-6, TNF-α, IL-4, MCP-1) in the intestine and serum, which is consistent with previous findings and observations of lipopolysaccharide-induced enteritis in vitro." (PMID 36759839, 2023). "Levels of the inflammatory factors IL-6 and TNF-α were significantly increased in the colon tissue of mice in the DSS group (P < 0.05) compared with those in control mice, which was suggestive of enteritis." (PMID 34901119, 2021). "For SN’s effect on intestinal humoral immunity, sinomenine hydrochloride may suppress proinflammatory cytokines (such as TNF-α) and increase anti-inflammatory cytokine IL-10 during DSS-induced enteritis in mice." (PMID 34887862, 2021). "Recent studies have shown that IL-1β and TNF-α can be proinflammatory cytokines in IBD, whereas IL-10 has been demonstrated to play a vital role in the control of inflammation and prevention of enteritis." (PMID 31341536, 2019). "In addition, the impact of the DSS exposition on the colon length and the fecal lipocalin level, in relation with TNFα synthesis, was comparable between the two groups, which supports solely the involvement of DSS in the induction and severity of enteritis without any detectable role for MCMV." (PMID 36560599, 2022).
acute liver failure (69 papers, 2006 to 2025). Rapid deterioration of liver function causing encephalopathy and coagulopathy. "Lastly, we examined responses to LPS and D-Gal, which cause acute liver failure through TNF-α-dependent hepatocyte apoptosis." (PMID 39853307, 2025). "NINJ1 deficiency also alleviated LPS/D-galactosamine-induced acute liver failure by reducing TNF-α-induced hepatocyte apoptosis." (PMID 36835580, 2023). "Inflammatory cytokines such as TNF-α, IL-1β and IL-6 are the key pathogenic factors of LPS/d-GalN-induced acute liver failure." (PMID 35645173, 2022). "In the context of acute liver failure, high levels of circulating IL-6 and TNFα are associated with impaired outcome in some studies, while in the hepatic compartment itself IL-6 seems to be protective as it downregulates TNFα-induced hepatic apoptosis." (PMID 34504196, 2021). "Since ConA is known to cause acute liver failure via an immunologic activated cytokine response syndrome with TNF-α and INF-γ as the pivotal mediators, these data implied that AKT1-MSCs had a superior protective effect on immune-mediated hepatitis." (PMID 31889917, 2019). "Poly I:C-treated animals with RIPK1-deficient hepatocytes developed the usual symptoms of acute liver failure accompanied by an enhanced systemic release of TNF-α, which was responsible for hepatocyte death." (PMID 30622241, 2019). "This is consistent with previous work where allopurinol alleviated the elevated liver malondialdehyde and TNFα associated with acute liver failure induced by thioacetamide in rats." (PMID 25889404, 2015). "In our experimental findings, we observed an elevation in the production of inflammatory cytokines—specifically TNF-a and IL-1—in a mouse model of acetaminophen-induced acute liver failure." (PMID 38892435, 2024). "The increase in TNF during the course of APAP-induced acute liver failure appears to be a crucial event in determining its outcome." (PMID 39771072, 2024). "The PPARδ agonist GW501516 improves survival in a mouse model of acute liver failure induced by LPS/D-GalN, primarily by suppressing the expression of pro-inflammatory cytokines such as TNF-α, IL-6, and NOS2 in vivo." (PMID 39519830, 2024). "The results demonstrated that among numerous abnormal substances that changed in acute liver failure, elevated estrogen levels and tumor necrosis factor-α were the main factors mediating the downregulation of OCT2 and MATE1." (PMID 38137535, 2023). "In a previous study, MSCs reduced liver injury and lowered IL-1β, IL-6, and TNF-α levels in a lipopolysaccharide-induced acute liver failure rat model." (PMID 35765490, 2022). "Activation of T cells and macrophages are observed in the initiation of acute liver failure, which induce the release of proinflammatory cytokines, such as tumor necrosis factor (TNF)-α." (PMID 36289761, 2022). "In this study, SS pretreatment effectively reduced NO, TNF-α, IL-1β, and IL-6 secretion in paracetamol-induced acute liver failure." (PMID 34199606, 2021). "To further study the role of OTUB1 in TNF responses of hepatocytes, we employed the DGal/LPS model, which induces TNF-dependent hepatocyte death and acute liver failure." (PMID 33712742, 2021). "In contrast to listeriosis, treatment with TNF or lipopolysaccharide (LPS) in combination with D-Galactosamine (D-Gal) mediates hepatocyte apoptosis and acute liver failure." (PMID 33712742, 2021). "In a recent study, increased brain efflux of IL-1β, TNFα, and IL-6 was identified in patients with uncontrolled intracranial hypertension due to acute liver failure." (PMID 32178308, 2020). "The protective ability of TNF-α/LPS MDSCs highlights the possible therapeutic role of MDSCs in patients with APAP-induced acute liver failure." (PMID 33250891, 2020). "It has also been reported that TNF-a-targeting aptamer has anti-inflammatory effects and has been proven to reduce TNF-a-mediated acute lung injury and acute liver failure." (PMID 32486412, 2020).
acute liver failure (continued). "We found that A. muris was enriched in acute liver failure rats, and its relative abundance positively correlated with the level of TNF-α." (PMID 31996423, 2020). "In conclusion, the current feasibility study demonstrated that UDCA reduced the expression of TNF-a and Il-6 during the priming phase of liver regeneration, in a setting of acute liver failure." (PMID 33489534, 2020). "Whereas TNF-α is most commonly viewed as a pro-inflammatory agent in acute liver failure, IL-6 can directly protect hepatocytes from oxidative stress after APAP toxicity, and both have long been known to stimulate liver regeneration." (PMID 32825435, 2020). "Specific inhibition of TNF-α, as well as other cytokines and chemokines in the setting of acute liver failure have shown to ameliorate inflammation and liver damage." (PMID 29795632, 2018). "TNFα and interleukin 1 beta (Il-1b) have been shown to be upregulated in brain tissue during acute liver failure in mice." (PMID 28801579, 2017). "Together, these data identify A20 as an essential protein protecting mice from TNF-induced hepatocyte apoptosis and acute liver failure in vivo." (PMID 27253414, 2016). "Elevations of the proinflammatory cytokines interleukin (IL)-1β, IL-6, and tumor necrosis factor alpha (TNFα) are observed in both patients and in rodent models of acute liver failure." (PMID 27561705, 2016). "It has been demonstrated in our previous study that the TNF-mediated excessive immune cascade response resulted in massive hepatocyte apoptosis and impaired hepatocyte proliferation during the development of acute liver failure." (PMID 23874752, 2013). "We demonstrated that a long-acting TNF antagonist (soluble TNF receptor: IgG Fc [sTNFR:IgG-Fc]) prevented/reduced development of acute liver failure by blocking the TNF/TNFR1 (TNFRp55) pathway." (PMID 23874752, 2013). "Endotoxin and inflammatory cytokines are important mediators in acute liver failure, and IL-1 and TNF-α are involved in its pathogenesis." (PMID 22844472, 2012). "During the development of acute liver failure, TNF-mediated over-immune cascade response may contribute to massive hepatocyte apoptosis and impaired hepatocyte proliferation." (PMID 35432526, 2022). "In our previous study, G-Rg1 could significantly reduce liver damage in a murine model with CCl4-induced acute liver failure through inhibiting TNF-α-induced and caspase-dependent hepatocellular apoptosis." (PMID 33628094, 2021). "There is evidence which demonstrated that Ephedrine has a potent anti-inflammatory activity against D-GalN/LPS-induced acute liver failure in rats, and this comprehensive anti-inflammatory effect may result from the inhibition of TNF-α production." (PMID 33959188, 2021). "The study on madecassoside found that it could ameliorate drug-induced acute liver failure by reducing inflammation (TNF-α ↓, IL-1β ↓, IL-6 ↓, iNOS ↓, COX-2 ↓) and oxidative stress (SOD ↑, CAT ↑, GPx ↑, Nrf2 ↑, HO-1 ↑)." (PMID 33013406, 2020). "Moreover, Itch deficiency renders mice resistant to tumor necrosis factor-α (TNF-α)-induced acute liver failure in three distinct models." (PMID 31623112, 2019). "TNFα was considered to play a role in hepatocytes apoptosis and liver injury and further triggered Bax activation and cleavage of caspase-9 and caspase-3 in acute liver failure (ALF)." (PMID 31921708, 2019). "It is well recognized that TNF-α is one of the key mediators in endotoxemic acute liver failure." (PMID 29795632, 2018). "It was reported that TNF-α production was increased in acute liver failure (ALF)." (PMID 26516376, 2015). "Similarly, anti-TNF-α antibodies were shown to attenuate BBB permeability via restored expression of BBB tight junction proteins in rat model of acute liver failure." (PMID 25784952, 2015).